LPL (lipoprotein lipase)
Diseases named in the same sentence as LPL in open-access papers (continued):
Sharing a sentence is not in itself a finding about the gene and the disease.
glioma (5 papers, 2019 to 2024). A benign or malignant brain and spinal cord tumor that arises from glial cells (astrocytes, oligodendrocytes, ependymal cells). "Confocal immunofluorescence microscopy studies on glioma and normal brain from wild-type and Gpihbp1–/– mice, along with the brain from an Lpl–/– mouse carrying a skeletal muscle–specific human LPL transgene (MCK)." (PMID 31169500, 2019). "Third, the most highly upregulated fatty acid metabolism gene in human gliomas, compared to normal brain tissue, is LPL." (PMID 31169500, 2019). "Documenting GPIHBP1 and LPL in glioma capillaries, combined with the discovery that TRL-derived nutrients are taken up and utilized by glioma cells, opens a new chapter in glioma metabolism research." (PMID 31169500, 2019). "Second, gliomas contain large numbers of macrophages (F4/80-expressing cells), and macrophages are known to express LPL." (PMID 31169500, 2019). "However, a recent study showed that GPIHBP1 is expressed in the capillaries of mouse and human gliomas, and seems to be involved in LPL production." (PMID 31863022, 2019). "Given the presence of GPIHBP1-bound LPL on glioma capillaries, we suspected that we might find evidence of TRL margination and processing in gliomas." (PMID 31169500, 2019). "To determine whether LPL is bound to GPIHBP1-expressing capillaries of gliomas, we performed immunohistochemical studies, taking advantage of an affinity-purified goat antibody against mouse LPL." (PMID 31169500, 2019). "The expression of GPIHBP1 in glioma capillaries was intriguing, but the crucial issue is whether LPL would be bound to the GPIHBP1." (PMID 31169500, 2019). "No one, as far as we are aware, had ever considered the possibility that gliomas might be capable of taking up and utilizing nutrients from LPL-mediated intravascular processing of TRLs." (PMID 31169500, 2019). "The colocalization of GPIHBP1 and LPL in the capillaries of gliomas implied that we might find evidence for TRL margination and processing in these tumors." (PMID 31169500, 2019). "Lipoprotein lipase (LPL) colocalizes with GPIHBP1 in glioma capillaries." (PMID 31169500, 2019). "Importantly, the GPIHBP1 in glioma capillaries captures locally produced LPL." (PMID 31169500, 2019). "Finally, it would be desirable to investigate whether the presence of GPIHBP1 and LPL in glioma capillaries could be exploited for patient care." (PMID 31169500, 2019). "We hypothesized that GPIHBP1-expressing endothelial cells of gliomas could capture LPL." (PMID 31169500, 2019). "Additional immunohistochemistry studies on mouse gliomas revealed that LPL colocalizes with GPIHBP1 on glioma capillaries, just as LPL colocalizes with GPIHBP1 in the capillaries of heart and brown adipose tissue." (PMID 31169500, 2019). "LPL was not present in the capillaries of the normal brain or in the capillaries of gliomas from Gpihbp1–/– mice." (PMID 31169500, 2019). "In the current study, we sought to determine whether glioma capillaries express GPIHBP1 and, if so, whether it binds LPL and facilitates TRL margination and the lipolytic processing of TRLs." (PMID 31169500, 2019). "Glioma and brain sections (10-μm-thick) were fixed with 3% PFA and then stained with a mAb against mouse GPIHBP1 (11A12; green), a goat antibody against mouse LPL (red), and a rabbit antibody against CD31 (white)." (PMID 31169500, 2019). "The binding of LPL to GPIHBP1 was specific: the LPL-specific goat antibody did not detect LPL in the capillaries of gliomas in Gpihbp1–/– mice, nor did it detect any LPL in macrophages or hippocampal neurons of Lpl–/–MCK-hLPL mice." (PMID 31169500, 2019). "The GPIHBP1 might capture locally produced LPL, allowing for TRL margination and TRL processing, and thereby providing a source of lipid nutrients for glioma cells." (PMID 31169500, 2019).
glioma (continued). "It would also be desirable to determine whether the uptake of TRL-derived nutrients in gliomas correlates with the levels of GPIHBP1 and LPL in glioma capillaries (as quantified with LPL- and GPIHBP1-specific antibodies tagged with different lanthanide metals)." (PMID 31169500, 2019). "We also found that LPL could be detected in some of the macrophages in mouse gliomas and in normal brain of wild-type mice, but not in the brain of Lpl–/–MCK-hLPL mice." (PMID 31169500, 2019). "LPL colocalizes with GPIHBP1 and CD31 in the capillaries of gliomas; GPIHBP1 and LPL were absent from normal brain capillaries and from glioma capillaries in Gpihbp1–/– mice." (PMID 31169500, 2019).
hyperlipoproteinemia (5 papers, 2016 to 2025). An elevated concentration of lipoproteins. "Eighteen Miniature schnauzers, a breed known to have hyperlipoproteinemia caused by deficient LPL activity, were analyzed for lipid content and lipoprotein fractions." (PMID 39858256, 2025). "Although LPL variants are rare, WES is important to discover the monogenic and oligogenic genetic patterns in severe hyperlipoproteinemia, a challenge now predigested by the access to next-generation sequencing." (PMID 35923617, 2022).
Hypoglycemia (5 papers, 2018 to 2025). A decreased concentration of glucose in the blood. "Accordingly, it is unlikely that the observed hypoglycaemia and hyperinsulinaemia in Angptl4−/− mice are linked to loss of inhibition of LPL activity in islet cells, whether via ANGPTL4 that is produced in the pancreas or elsewhere." (PMID 29502266, 2018). "A recent study has revealed that hypoglycemia in hepatocyte-specific G6pc1 deficient mice impairs very-low-density lipoprotein (VLDL) catabolism, which was suggested to be caused by decreased lipoprotein lipase (LPL) activity." (PMID 34091064, 2021). "However, the use of insulin in non-diabetic patients carries a risk of hypoglycemia, and the long-term use of heparin may lead to overconsumption of lipoprotein lipase." (PMID 40101052, 2025).
preeclampsia (5 papers, 2011 to 2022). Preeclampsia is a hypertensive disorder of pregnancy that is characterized by new-onset hypertension with proteinuria presenting after 20 weeks of gestation, and depending on mild or severe forms may initially present with severe headache, visual disturbances, and hyperreflexia. "Glutathione S-transferase P1 (GSTP1), endothelial nitric oxide synthase (eNOS), and lipoprotein lipase (LPL) constitute three major detoxification enzymes that have been studied in pregnancy, as putative predisposing factors to preeclampsia." (PMID 20836743, 2011). "To this end, we have utilized the transmission disequilibrium test or TDT developed as a test for linkage between a complex disease, such as preeclampsia and a genetic marker, such as the polymorphic alleles of the GSTP1, eNOS, and LPL genes." (PMID 20836743, 2011). "We next studied the distribution of the frequencies of GSTP1, eNOS, and LPL genotypes in the subgroups of the mothers, fathers, and children of the preeclampsia and normal control groups." (PMID 20836743, 2011). "In addition, a dysregulation of lipoprotein lipase (LPL) activity seems to also be involved in the pathogenesis of preeclampsia, although there are still contradictory studies on its implication." (PMID 35631313, 2022). "The GSTP1 polymorphism with its variant Val105 allele is not sufficient to clearly confer an increased risk for preeclampsia, neither the eNOS polymorphism with the variant 298Asp allele, nor the LPL gene polymorphism with the -93G variant allele." (PMID 20836743, 2011). "In preeclampsia, there is a higher serum FFA to albumin ratio and increased LPL activity, resulting in enhanced endothelial uptake of FFA, which are further esterified and accumulated into triglycerides pools, secondary to a decrease in intracellular lipase." (PMID 35631313, 2022). "We hypothesized that these gene polymorphisms might constitute a basis for the triggering events leading to preeclampsia, by affecting the activity of biotransformation enzymes (GSTP1 and eNOS) in detoxifying processes and/or the endothelial function (LPL)." (PMID 20836743, 2011). "However, the transmission rates of the parental alleles to neonates studied by the transmission disequilibrium test, disclosed no increased rate of transmission to preeclampsia children for the variant alleles of Val105 GSTP1, 298Asp eNOS, and -93G LPL." (PMID 20836743, 2011).
xanthoma (5 papers, 2004 to 2024). A non-neoplastic disorder characterized by a localized collection of histiocytes containing lipid. "After the initiation of the MCT-enriched diet, his xanthomas abated over time, and there were no other documented LPL-related complications." (PMID 37630727, 2023).
amyloid (4 papers, 2021 to 2026). "Patients with known LPL/WM or other IgM monoclonal gammopathy should be evaluated for possible amyloidosis in certain situations, and patients diagnosed with IgM-associated amyloidosis should complete an additional evaluation for lymphoma." (PMID 36591532, 2022). "Most recently, LPL has also been shown to bind to amyloid beta protein (Aβ), the peptide which comprises AD amyloid plaques, and promote cell-surface association and uptake of Aβ in mouse primary astrocytes, providing an alternative mechanism of how LPL might play a role in AD." (PMID 38455763, 2024). "LPL supports this process by enhancing lipid metabolism to fuel ATP production, thereby promoting the clearance of amyloid deposits." (PMID 41484634, 2026). "Patients with LPL/WM and amyloidosis have significantly worse overall survival than patients with LPL/WM alone (2.5 years vs. 12.1 years; HR 5.9)." (PMID 36591532, 2022).
B-cell lymphomas (4 papers, 2017 to 2025). "The differences in IGH, IGK and IGL gene rearrangement rates in DLBCL, MALT, FL, CLL, MCL, MZL, plasmocytoma and LPL indicated that analysis of the gene rearrangement rate could be clinically important in the classification of different B-cell NHLs." (PMID 29100365, 2017).
diabetic kidney disease (4 papers, 2019 to 2025). Progressive kidney disorder caused by vascular damage to the glomerular capillaries, in patients with diabetes mellitus. "Regarding the LPL polymorphism, several studies investigated an association between the LPL S447X and T2DM, and the results imply the protective effect of the S447X polymorphism on T2DM incidence, as well as protection against diabetic nephropathy." (PMID 36605456, 2023). "Altogether, this suggests a potential role for ANGPTL4 in DN perhaps through its role in inhibiting LPL activity and promotes ANGPTL4 as a biochemical marker for the detection of a diabetic kidney disease in patients with T2D." (PMID 31772941, 2019).
hyperandrogenemia (4 papers, 2010 to 2023). "These parameters slightly impact differences in lipid profiles among studies since insulin is one of the main regulators of lipoprotein lipase activity, and hyperandrogenemia has an independent function in lipoprotein and lipid metabolism." (PMID 38024834, 2023). "Because insulin is one of the major regulators of lipoprotein lipase activity and hyperandrogenemia has an independent role in lipoprotein and lipid metabolism, differences in lipid levels in various studies are somewhat influenced by these factors." (PMID 27351028, 2016).
ischemia (4 papers, 2019 to 2025). A hypoperfusion of the BLOOD through an organ or tissue caused by a PATHOLOGIC CONSTRICTION or obstruction of its BLOOD VESSELS, or an absence of BLOOD CIRCULATION. "ANGPTL4 reduces renal injury and proteinuria by binding to glomerular endothelial ανβ5 integrin and inactivating LPL activity and promotes angiogenesis in ischemia." (PMID 35646873, 2022). "In brain regions less affected by ischemia, such as the ischemic penumbra of I-PCX, the number of upregulated lipids was reduced to four species, and LPE 22:6 was the only LPL identified." (PMID 36355158, 2022).
lymphoma (4 papers, 2020 to 2022). A malignant (clonal) proliferation of B- lymphocytes or T- lymphocytes which involves the lymph nodes, bone marrow and/or extranodal sites. "The increased TAG level in DCs of lymphoma mouse or patients with lymphoma is mainly realized by regulating the expression levels of scavenger receptor A, lipoprotein lipase, and fatty acid-binding protein 4, and promoting the uptake of TAG in BMDCs and moDCs." (PMID 33732237, 2021). "In a Norwegian study, CAD-associated LPD was found to be distinct from LPL, MZL, and other previously recognized lymphoma entities, with the absence of an MYD88L265P mutation." (PMID 32728060, 2020). "Eight patients underwent immunohistochemistry of renal tissues, of which three patients (CLL, n=1; LPL, n=1; WM, n=1) had confirmed lymphoma infiltrates, and the infiltrating cells in the remaining five patients (CLL, n=1; MALT lymphoma, n=2; MGUS, n=2) were considered unrelated to lymphoma." (PMID 36172352, 2022).
migraine (4 papers, 2023 to 2025). "Lipoprotein lipase (LPL) enhancement was significantly causally associated with a lower risk of migraine (OR = 0.89, 95% CI: 0.83–0.96, p = 0.0016)." (PMID 40994718, 2025). "LPL enhancement genetic mimicry was also associated with decreased migraine risk in both FinnGen (OR = 0.82, 95% CI: 0.69–0.96, p = 0.01) and Choquet datasets (OR = 0.91, 95% CI: 0.83–0.99, p = 0.03)." (PMID 39901103, 2025). "This research study provided compelling genetic evidence supporting the potential of HMGCR inhibition and LPL enhancement in reducing the risk of migraines." (PMID 37596566, 2023). "This study presents novel findings regarding the causal association between the enhancement of LPL activity and the risk of migraines." (PMID 37596566, 2023). "Enhanced LPL activity may suppress the inflammatory response, attenuating neuroinflammation and dampening the inflammatory cascade associated with migraines." (PMID 37596566, 2023). "Similarly, genetic mimicry of LPL enhancement was associated with a lower risk of migraine in the FinnGen dataset (OR = 0.82, 95% CI: 0.69–0.96, p = 0.01) and the Choquet dataset (OR = 0.91, 95% CI: 0.83–0.99, p = 0.03)." (PMID 37596566, 2023). "Additionally, LPL inhibitors have shown significant associations with migraine risk." (PMID 39204161, 2024). "Interestingly, our study revealed a causal association between lower Apo-A1 levels and a reduced risk of migraine, the increased LPL activity could contribute to alterations in Apo-A1 levels, which in turn may influence the risk of migraine." (PMID 37596566, 2023). "Among the 10 lipid-lowering drug targets investigated, LPL and HMGCR showed significant associations with migraine risk." (PMID 39901103, 2025). "Additional studies involving in vitro experiments, animal models, and clinical trials are needed to unravel the intricate molecular pathways and confirm the therapeutic potential of LPL modulation in reducing migraine occurrence." (PMID 37596566, 2023). "In the study, it was observed that among the 10 lipid-lowering drug targets investigated, LPL and HMGCR showed significant associations with migraine risk." (PMID 37596566, 2023). "For TG and migraine within the LPL gene, the respective posterior probabilities were 1.45%, 0.35%, and 80.73%." (PMID 37596566, 2023). "Further research is needed to better understand the underlying mechanisms, and the potential effectiveness of HMGCR inhibitors and LPL activators in migraine treatment should be evaluated through preclinical and clinical trials." (PMID 37596566, 2023). "For Apo-B and migraine within the LPL gene, the respective posterior probabilities were 1.36%, 0.59%, and 69.64%." (PMID 37596566, 2023). "Additionally, this study highlights HMGCR and LPL as promising drug targets for the treatment of migraines." (PMID 37596566, 2023). "The causal association between genetic mimicry of LPL enhancement using Apo-B level and migraine was not statistical significance because of the limited number of available instruments for this analysis." (PMID 37596566, 2023). "This suggests that LPL and HMGCR have the potential to serve as candidate drug targets for the treatment or prevention of migraine." (PMID 40994718, 2025).
thyroid (4 papers, 2016 to 2021). "In addition, thyroid hormones also increase the activity of lipoprotein lipase, which hydrolyzes TG-rich lipoproteins and accelerates the transfer of cholesterol esters from these lipoproteins to HDL and reduces circulating TG levels." (PMID 33305315, 2021). "The lack of thyroid hormones is associated with reduced clearance of TG-rich particles, due to attenuated lipoprotein-lipase (LPL) and hepatic lipase (HL) activities, and increased production of very-low density lipoprotein (VLDL) particles." (PMID 31920978, 2019). "Studies have also indicated that thyroid hormones may affect HDL metabolism by increasing the cholesteryl ester transfer protein activity and that they may also stimulate lipoprotein lipase." (PMID 28008862, 2017).
thyroid cancer (4 papers, 2021 to 2025). "Elevated LPL expression was also observed in the GEO dataset (GSE104006) in thyroid cancer specimens." (PMID 40650680, 2025). "Consistently, LPL expression elevation in thyroid cancer specimens were also observed in a GEO dataset (GSE104006)." (PMID 34976793, 2021). "Some studies found that LPL, FATP2, and CPT1A can all promote the migration of thyroid cancer cells, while USF-2 inhibits the proliferation of normal thyroid cells and thyroid cancer cells." (PMID 38189054, 2023). "In order to verify that LPL, FATP2 and CPT1A involve in metastasis of thyroid cancer, these genes were overexpressed in BHP10-3 cells." (PMID 34976793, 2021). "Together, LPL, FATP2 and CPT1A activate fatty acid metabolism to promote thyroid cancer progression." (PMID 34976793, 2021). "In addition, ectopic overexpression of LPL, FATP2 and CPT1A can each promote the migration of thyroid cancer cells." (PMID 34976793, 2021).
viral infection (4 papers, 2011 to 2024). "After virus infection, the LPL activity at the cell surface of each cell type was significantly higher than in the control cells, which indicates that all three cell types can be used to generate functional LPL." (PMID 28969646, 2017). "In the absence of THL, LPL inhibited viral infection by two orders of magnitude, whereas, in the presence of THL, LPL also decreased infection levels, but only by one order of magnitude." (PMID 22039521, 2011).
autoimmune disease (3 papers, 2024 to 2025). A disorder resulting from loss of function or tissue destruction of an organ or multiple organs, arising from humoral or cellular immune responses of the individual to their own tissue constituents. "The patient with SMZL commonly presents with marked splenomegaly, higher number of leukocytes, and lack of hyper viscosity symptoms, while the patient with LPL/WM is susceptible to hyper viscosity symptoms and autoimmune diseases." (PMID 38335376, 2024). "However, the heterozygous patient carrying the LPL:c.596delC:p.Ser199Phefs*8 variant had no personal history of autoimmune disease, but their father had vitiligo." (PMID 39858602, 2025).
cardiac hypertrophy (3 papers, 2015 to 2018). "Furthermore, cardiac hypertrophy and increased mortality are linked to cardiac deposition of lipid in a transgenic mouse model overexpressing lipoprotein lipase (LPL) when fed a HFD." (PMID 30134607, 2018).
Cerebral ischemia (3 papers, 2020 to 2025). Restriction of arterial blood supply to the brain associated with insufficient oxygenation to support the metabolic requirements of the tissue. "In cerebral ischemia, the upregulation of LPL expression may be involved in lipid recycling and neural remodeling." (PMID 41002434, 2025).